BRCA1 (BRCA1 DNA repair associated)
Diseases named in the same sentence as BRCA1 in open-access papers (continued):
Sharing a sentence is not in itself a finding about the gene and the disease.
tumor (continued). "In one case with a deletion of exon 20 in BRCA1, re-evaluation of the bioinformatic variant calls revealed the deletion also in the tumor DNA and led to a correction of the initial diagnostic report." (PMID 34202525, 2021). "For example, the U.S. Food and Drug Administration has approved numerous PARP inhibitors for treating certain tumor types harboring either germline or somatic mutations in BRCA1/2." (PMID 34356050, 2021). "A correlation between the variant localization in the putative BCCRs and OCCRs of BRCA1 and type of tumor was observed only in three BC and two OC patients." (PMID 34178674, 2021). "For instance, as homology-directed DNA repair is crucial for BRCA1′s tumor-suppressing activity, it is often used to assess the functional consequences of BRCA1 variants." (PMID 33879063, 2021). "A pathogenic tumor BRCA1/2 DNA sequence variant in tumor specimens was found in 53 (37.9%) patients." (PMID 34202525, 2021). "This is consistent with the data derived from targeted deletion of Pdgfrβ, and these results further confirm that inhibition of Pdgfrβ-Pkcα signaling promotes Brca1-deficient tumor cell death and MET." (PMID 33478572, 2021). "Collectively, these results show that DNA end resection inhibition leads to PARPi resistance in BRCA1-deficient tumor cells through the restoration of BRCA1-independent HR." (PMID 34439286, 2021). "HR is required for DSB repair, and HR-deficiency is a typical pathological feature of the BRCA1/2-mutated tumor and enables enhanced response to PARP1 inhibition due to synthetic lethality." (PMID 34631532, 2021). "As tumor suppressor genes, mutations of BRCA1 (MIM 113705) and BRCA2 (MIM 600185) are closely related to the development of BC." (PMID 34926254, 2021). "Strikingly, in patients < 40 years, 82.1% had a BRCA1-deficient phenotype (BRCA1-null tumor or somatic BRCA1 promoter hypermethylation)." (PMID 33568222, 2021). "Taking into account the known associations between BRCA1/2-related tumors and worse tumor biology, all analyses were repeated excluding BRCA1/2 carriers." (PMID 34857041, 2021). "To determine the role of Pdgrfβ in Brca1-deficient tumorigenesis, we knocked out Pdgfrβ in p18−/−;Brca1MGKO primary tumor cells by using the CRISPR/Cas9 system." (PMID 33478572, 2021). "BRCA1 DNA repair associated (BRCA1) is a tumor suppressor which maintaining genomic stability and associates with RNA polymerase II." (PMID 34130650, 2021). "The aim of this study was to compare tumor BRCA1/2 status with germline mutational status to evaluate the reliability of tumor testing results." (PMID 34202525, 2021). "With the exception of the large CNVs, the BRCA1/2 VAF in tumor samples for confirmed germline variants (PV and VUS) ranged from 5% to 94%." (PMID 33030818, 2021). "One woman with constitutional path_MMR variant had a MMR proficient tumour; she also had a constitutional BRCA1 pathogenic variant." (PMID 32917768, 2021). "This study not only reveals the molecular mechanism of BRCA1 in suppressing EMT but also tests the efficacy of inhibitors that target PDGFRβ-PKCα signaling on suppressing BRCA1-deficient tumor initiation and progression." (PMID 33478572, 2021). "PARPis have achieved great successes in the treatment of BRCA1/2-mutated tumours, such as ovarian cancer and BC." (PMID 33832512, 2021). "A phase II clinical trial demonstrated responses to olaparib across different tumor types associated with germline BRCA1/2 mutations." (PMID 33959007, 2021). "Foundation Focus® CDx tests tumor DNA to detect mutations in BRCA1/2 genes and the percentage of the genome affected by LOH." (PMID 34912215, 2021). "The same genomic alterations can be a target for a chemotherapy agent carboplatin, which is known to double the objective tumor response rate in women with metastatic BC and germline BRCA1/2 mutations." (PMID 32881420, 2020).
tumor (continued). "By stimulating ATR–CHK1 signalling, activation of the G2/M and S/G2 cell-cycle checkpoints, at least in part, overcomes the lethal block caused by Brca1 deficiency through suppression of the mitotic catastrophe and promotes tumour initiation." (PMID 32591500, 2020). "BRCA1-null tumor cells were distributed amongst distinct clusters associated with C13, basal cells during gestation (C13:Bsl-G) and C12, basal cells (C12:Bsl), consistent with our initial observations of these cells having increased expression of basal genes." (PMID 32840210, 2020). "Breast cancer type 1 susceptibility protein (BRCA1), a tumor suppressor, induces DNA double-strand break repair by homologous recombination, protecting DNA replication forks from attrition." (PMID 32964028, 2020). "The expression of all approximately 7500 probes was able to distinguish BRCA1-associated tumours from BRCA2-associated tumours." (PMID 33081408, 2020). "NGS testing of the mutational BRCA1/2 status is recommended on both tumour DNA and germline DNA (peripheral blood cells), given that most of the BRCA1/2 mutations detected in tumours are germline." (PMID 33123697, 2020). "In an attempt to account for BRCA1-associated tumour phenotypes, investigators have explored BRCA1-associated gene expression profiles in hormonal negative tumours." (PMID 33081408, 2020). "This underlies the molecular rationale and the significant clinical benefit of PARPis in BRCA1/2 mutation carriers and patients with HR-deficient tumours." (PMID 32833070, 2020). "In the SOLO-1 trial, Myriad test was used to confirm the centrally germline BRCA1/2 mutation status, while the tumor BRCA1/2 mutation status was assessed retrospectively using a Foundation Medicine platform." (PMID 32596142, 2020). "BRCA1 protein with mutations is known to have a shorter half-life, which results in impaired DNA damage repair and tumor progression." (PMID 32079144, 2020). "The survival analysis revealed PEG3 mutant patients had worse survival outcome after controlled for multiple factors including age, tumor stage and mutations of BRCA1, BRCA2 and POLE." (PMID 32729618, 2020). "In ovarian cancers, BRCA1/2-mutated tumours are associated with increased levels of tumour-infiltrating lymphocytes." (PMID 32283785, 2020). "He underwent somatic tumor analysis that showed pathogenic BRCA1 mutation (c.68_69delAG), later proved to be germline." (PMID 32377194, 2020). "It has therefore been proposed that loss of BRCA1 function in basal stem cells results in tumor formation associated with a block in luminal differentiation." (PMID 32863939, 2020). "The difference observed in the size of the gene lists suggested that BRCAx tumours are more similar to tumours from BRCA2 pathogenic variant carriers than BRCA1 pathogenic variant carriers." (PMID 33081408, 2020). "Patients with BRCA1 loss have reduced life expectancy due to higher tumour grade and advanced clinical stage." (PMID 32686903, 2020). "Mutational analysis of tumor tissue using next generation sequencing allowed the detection of both germline and somatic BRCA1/2 mutations." (PMID 32856862, 2020). "Tumor cell content showed a strong linear correlation with BRCA1 CpG allele methylation rate for hypermethylated cases when using WGS specific estimates also accounting for possible subclonality (r2 = 0.84, slope = 0.90)." (PMID 32719340, 2020). "Mutation in the NLSs domain causes accumulation of BRCA1 in the cytosol and reduce the tumor suppressor activity of this protein." (PMID 33013205, 2020). "Analysis of protein levels in BRCA1-deficient tumours indicated that a high protein expression level of NOTCH1 correlated with TNBC incidence." (PMID 32591500, 2020).
tumor (continued). "Lisowska and colleagues were able to identify 423 genes significantly (p < 0.001) differentially expressed in BRCA1-associated tumours." (PMID 33081408, 2020). "In comparison, identifying the intriguing tissue-and gender-specificity linked with BRCA1 tumour suppression is a less travelled route." (PMID 34803264, 2020). "We report, to our knowledge for the first time, a significant association between BRCA1 promoter hypermethylation and PD-L1 expression, in both tumor and immune cells." (PMID 32235500, 2020). "The remarkable similarity in mutation profiles in BRCA1-deficient tumour cells and BRCA1-deficient C. elegans suggests that the mechanisms leading to these mutations are evolutionarily conserved." (PMID 32680986, 2020). "In contrast, we presume that patients with somatic BRCA1/2 mutations demonstrate the effect of autophagy induction exclusively in the tumor cells containing the BRCA1/2 mutation." (PMID 33409454, 2020). "BRCA1/2 mutations were detected from formalin-fixed parafin-embedded tumor samples using the OncomineTM BRCA Research Assay on Personal Genome Machine Platform with Ion Reporter Software for sequencing data analysis." (PMID 32856862, 2020). "BRCA1 is a nuclear phosphoprotein of 1863 aa and tumor-suppressor, encoded by the BRCA1 gene located in 17q21." (PMID 32013256, 2020). "We find that brc-1-deficient animals accumulate mutations similar to BRCA1-deficient tumours (micro-homology-mediated deletions, tandem duplications and base substitutions), and we causally implicate polymerase theta in the emergence of structural variations." (PMID 32680986, 2020). "In 2009, a phase I clinical trial of olaparib was started, including ovarian and breast tumor patients (among other tumor types included) with germline BRCA1 or BRCA2 mutations." (PMID 32005245, 2020). "Of course, this would need further exploration, in particular in patients with BRCA1 pathogenic variant in the tumor (i.e., somatic BRCA1 pathogenic variant)." (PMID 32290274, 2020). "Our data in high glucose conditions, which we also previously reported, suggested that IGF-I circumvents tumour suppressive functions of BRCA1 by reducing its association with phosphorylated ACCA and upregulating FASN downstream of ACCA." (PMID 33212987, 2020). "Metastatic tumor samples from the liver contained 30 additional pathogenic mutations, including additional mutations in BRCA1 and BRCA2." (PMID 33198737, 2020). "The BRCA status of the tumor has been assessed in 10 patients with recurrent/progressive disease and revealed a somatic BRCA1 mutation in one case." (PMID 32144573, 2020). "Multiple studies have demonstrated the polyclonality of various reversal mutations, thus exerting selection pressure on tumor cells to restore BRCA1/2 activity and reduce PARPi sensitivity." (PMID 33324554, 2020). "HR is scheduled but weakened by WEE1 inhibitor through phosphorylation of CDK1 in BRCA1/2-deficient tumor cells." (PMID 33324554, 2020). "Germline mutations in BRCA1 are well known to increase the risk of developing breast and/or ovarian cancer, with somatic mutations of this tumour suppressor also identified in sporadic tumours." (PMID 33233707, 2020). "The trial prospectively examined three potential biomarkers of PARP inhibitor activity, a molecular signature of HR deficiency using HRDetect, RAD51 focus formation in a tumor biopsy at the end of treatment, and BRCA1 methylation." (PMID 32471999, 2020). "PARPi has limited off-target side effects as it only targets tumor cells that simultaneously have BRCA1/2 mutations, causing cell death." (PMID 32950050, 2020). "Immune signatures were also significant (p < 0.05) in the presence of tumor cytoreduction, BRCA1/2 mutation, and COL2A1 expression." (PMID 32156016, 2020).
tumor (continued). "Due to the DNA repair defect, BRCA1/2 deficient tumor cells are more sensitive to PARP inhibitors (PARPi) through the mechanism of synthetic lethality." (PMID 32563252, 2020). "Oncoplots with somatic SNVs showed a highly unique mutation pattern in each tumor with very different SNVs or mutated genes in both mice and human patients bearing BRCA1 mutations." (PMID 32978388, 2020). "It is well known that individual risks of BRCA1/2 mutation carriers can vary due to a number of factors, and additional genetic changes or genetic modifiers that can modify tumor predisposition." (PMID 32255263, 2020). "BRCA1-impaired (pathogenic carriers and hypermethylated BRCA1 promoter) tumours had 321 genes differentially expressed from basal-like sporadic tumours." (PMID 33081408, 2020). "In terms of failure patterns, many studies have compared ipsilateral and/or contralateral tumor recurrence in BRCA1 and BRCA2 mutation carriers and patients with sporadic cancers." (PMID 33019612, 2020). "The stabilization of replication forks in tumor cells is another pathway by which BRCA1/2 deficient tumor cells develop resistance to PARP inhibitors." (PMID 32180937, 2020). "Meanwhile, similar as the characteristics of germline BRCA1 mutation, BRCAness was also associated with higher tumor grade, hormone receptor negativity, and higher proportion of TNBC subtype according to our results." (PMID 33273622, 2020). "For many years, BRCA1/2 mutations were only screened on germline DNA, but now they are also searched at the tumor level to personalize treatment." (PMID 32481735, 2020). "ARIEL 2 enrolled platinum-sensitive EOC patients, assigned to one of three HR deficiency categories assessed on the most recent collected tumor sample: BRCA1/2 mutated, BRCA wild-type (BRCAwt) with LOH high, and BRCAwt with LOH low, respectively." (PMID 32455595, 2020). "Perhaps the best known example of such phenomenon involves mutations and/or low expression of BRCA1/2, whereby HR deficiency sensitizes tumor cells to inhibit PARP1, a critical mediator of the corresponding DNA single-strand break repair pathway." (PMID 33138032, 2020). "Of all patients with tumor BRCA1/2 variants, 54–74% are germline and 27–46% are somatic, i.e., present only in the tumor tissue." (PMID 33233347, 2020). "The term “BRCAness” describes BRCA1 or BRCA2 mutation phenocopies, which represent the situation in which a tumor cell has an HRR obstruction with a germline BRCA1 or BRCA2 deficiency." (PMID 32122376, 2020). "Double-strand breaks are usually repaired by error-free homologous recombination, a process that is inhibited in BRCA1/2 mutated tumors; these double-strand breaks can lead to apoptosis of cancer cells within the tumor." (PMID 32391281, 2020). "The tumor suppressor proteins encoded by the breast cancer genes BRCA1 and BRCA2 participate in the HR of double-strand DNA breaks." (PMID 31963730, 2020). "Results of circulating tumor DNA (ctDNA) testing and an additional testing platform that reported somatic/ germline status confirmed his germline BRCA1 variant." (PMID 32793315, 2020). "Based on these data, if any pathogenic or likely pathogenic variant is found in BRCA1/2 using a tumor-only NGS assay, additional germline testing is recommended." (PMID 31628423, 2020). "Tumour cells with BRCA1/2 gene mutations demonstrate increased sensitivity to platinum and poly (ADP-ribose) polymerase (PARP) inhibitors." (PMID 31813938, 2020). "PARP inhibitors induce targeted tumor cell death in homologous recombination repair-deficient cells (e.g., those with BRCA1/2 deficiency) through the exploitation of synthetic lethality." (PMID 32483276, 2020). "We here show that the mutational landscape of BRCA1 deficiency in C. elegans closely resembles that of BRCA1-deficient tumours." (PMID 32680986, 2020).
tumor (continued). "Therapies are personalized and depend on several factors, including tumor subtype, tumor stage, genomic markers, patient age, general health, menopause status, and even the presence of mutations known as BRCA1 or BRCA2." (PMID 33202711, 2020). "This randomised, double-blinded, placebo-controlled phase 3 clinical trial distinguished three groups of patients in the order of increasing efficacy to niraparib: BRCAwt and HR-proficient tumours < BRCAwt and HR-deficient tumours < BRCA1/2 m tumours." (PMID 32833070, 2020). "It is also a known BC susceptibility gene shown to phosphorylate several tumour suppressors such as BRCA1, CHEK1 and TP5350,51." (PMID 32632202, 2020). "This assumption is based on the clinical observation that, after response to platinum-based chemotherapy, patients with tumours classed as “HR-proficient” benefit less from PARPis compared to patients with HR-deficient or BRCA1/2 mutant tumours." (PMID 32833070, 2020). "PARPi are also effective against other BRCA1/2-deficient tumor types such as pancreatic and prostate cancers." (PMID 33015624, 2020). "BRCA1 has been readily established as a tumor suppressor through epidemiological, mutational, and knockout mouse studies." (PMID 31923184, 2020). "Promoter hypermethylation was associated with reduced IHC BRCA1 protein expression (p = 0.005), and expression of Programmed death-ligand 1 protein (PD-L1) by tumor and immune cells (p = 0.03 and 0.011, respectively)." (PMID 32235500, 2020). "For tubo-ovarian cancer, an approach driven by histological tumor features has been adopted in a number of institutions given the strong association between high-grade serous morphology and BRCA1/2 mutations." (PMID 33117676, 2020). "The CD44+CD24−/low phenotype is associated with breast cancer 1 (BRCA1) mutational status and basal-like tumor status." (PMID 32316333, 2020). "The “Breast Cancer Type 1 susceptibility gene” (BRCA1, 17q21.31) is a tumor suppressor that acts as a caretaker gene, that is to say, it is responsible for repairing DNA lesions and mutations, such as double-strand breaks, together with other oncosuppressors." (PMID 32085420, 2020). "The sensitivity to PARP inhibitors (PARPi) is related to tumor-specific defects in homologous recombination (HR) and extends beyond BRCA1/2-related deficiencies." (PMID 33003546, 2020). "This confirmed a significantly higher prevalence of MF/MC tumours amongst BRCA2 mutation carriers compared with BRCA1 mutation carriers." (PMID 32022473, 2020). "Based on the assumption that BRCA-like events would have similar downstream effects on tumor biology as BRCA1/BRCA2 germline mutations, we quantified these effects based on somatic-mutation signatures and gene-expression profiles." (PMID 32997669, 2020). "BRIP1 is a member of the RecQ DEAH helicase family, and is encoded by BRIP1, a tumor suppressor gene involved in the DNA repair pathway, via its interaction with BRCA1." (PMID 32300589, 2020). "An older study showed that high CAIX protein level is related not only with triple-negative subtype, but also tumor size, tumor grade, chemotherapy resistance, worse OS, and BRCA1 mutation." (PMID 32212787, 2020). "Recent work has identified WGS signatures of HR deficiency with BRCA1/2 deficient tumours associated with distinct mutational signatures." (PMID 32471999, 2020). "The similarity of some sporadic tumours to BRCA1-associated tumours is consistent with those observations in tumours with hypermethylated BRCA1 promoters described in early studies." (PMID 33081408, 2020). "In this study, we used Multiplicom BRCA MASTR Dx assay for the detection of BRCA1/BRCA2 variants using DNA extracted from FFPE tumor samples, for which it has CE-IVD marking." (PMID 32850417, 2020). "Recent studies have shown that the efficacy of PARP inhibitors in epithelial ovarian carcinoma (EOC) is related to tumor-specific defects in homologous recombination (HR) and extends beyond BRCA1/2 deficient EOC." (PMID 33003546, 2020).